ACHE (acetylcholinesterase (Yt blood group))
Diseases named in the same sentence as ACHE in open-access papers (continued):
Sharing a sentence is not in itself a finding about the gene and the disease.
Alzheimer disease (continued). "The inhibition of the AChE enzyme using specific inhibitors has emerged as a promising therapeutic approach for managing a range of neurological disorders including Lewy body dementia and Alzheimer’s disease (AD)." (PMID 39765732, 2024). "In addition to this, triazolopyrimidine derivatives exhibit acetylcholinesterase (AChE) inhibitory properties, an important factor necessary for the treatment of Alzheimer’s disease (AD)." (PMID 38794119, 2024). "Indeed, donepezil, a second-generation AChE inhibitor, is used to treat Alzheimer’s disease due to its significant cholinesterase inhibitory activity." (PMID 36771160, 2023). "Additionally, the extract has demonstrated the potent inhibition of AChE, suggesting its potential utility in the prevention of neurodegenerative diseases, including Alzheimer’s disease." (PMID 38067623, 2023). "AChE inhibitors are the mainstay of symptomatic treatment for Alzheimer’s disease." (PMID 37241886, 2023). "According to the results of this investigation, elevated levels of AChE activity may have a role in the development of Alzheimer’s disease (AD)." (PMID 37368609, 2023). "In 2001, the Food and Drug Administration (FDA) approved the use and commercialization of galanthamine, an Amaryllidaceae alkaloid, under its salt form for the palliative treatment of mild to moderate Alzheimer’s disease symptoms due to its potential as an AChE inhibitor." (PMID 37629578, 2023). "Moreover, low AChE can result in a lower performance and reduced function of the brain in Alzheimer's disease because neurotransmitters are critically required in synapses for the transmission of nerve impulses." (PMID 38089182, 2023). "IFD simulation further complemented experimental AChE inhibition by delineating the potential mechanism of action for AChE inhibition, and highlighted 10d as a potential lead candidate to develop novel benzofuran-based anticholinesterase drugs in therapeutics of Alzheimer’s disease." (PMID 37630258, 2023). "Also, its inhibitory effects on key enzymes, including AChE (IC50: 12.80 μg/mL), α-amylase (IC50: 421.02 μg/mL) and CA II (IC50: 505.83 μg/mL) associated with diabetes, glaucoma and Alzheimer’s disease are extremely important." (PMID 37763342, 2023). "Two hypotheses of the mechanisms of Alzheimer’s disease occurrence involve (i) termination of neurotransmitters by two cholinergic enzymes, AChE and BChE, and (ii) β-amyloid formation by BACE-1." (PMID 38066118, 2023). "Acetylcholinesterase (AChE) is an enzyme in charge of the death of neurons in Alzheimer’s disease." (PMID 37103365, 2023). "Recent evidence suggests that both enzyme (AChE and BuChE) may have roles in the etiology and progression of Alzheimer’s disease (AD) in addition to the regulation of synaptic ChE levels in healthy brain." (PMID 37514236, 2023). "Previous findings indicated that aloe-emodin, the most active component of aloe species, could have neuroprotective effects against Alzheimer’s disease (AD) via inhibiting the activity of AChE and modulating oxidative stress." (PMID 36671023, 2023). "Keeping in mind the biological importance of benzimidazole and oxazole scaffolds, in this study, we designed and synthesized hybrid analogues based on benzimidazole-bearing oxazole derivatives to further explore the AChE and BuChE inhibition profiles for the better treatment of Alzheimer’s disease." (PMID 37894494, 2023). "When combining the inhibitory data from these three main enzymes that control Alzheimer’s disease occurrence, DL and DM had more than 90% inhibition against AChE and BChE and more than 60% inhibition against BACE-1 as two potential herbal extracts for reducing the risk of Alzheimer’s disease." (PMID 38066118, 2023). "AChE inhibitors can attenuate neuronal damage and death from cytotoxic insults and therefore might affect Alzheimer Disease pathogenesis." (PMID 36765125, 2023).
Alzheimer disease (continued). "H3R antagonist with additional AChE/BuChE inhibitory effect might improve cognitive functions in Alzheimer’s disease." (PMID 37242458, 2023). "The antioxidant EGCG from Camellia sinensis (green tea) was investigated to see whether it could enhance the inhibitory effects of huperzine A on AChE activity in Alzheimer’s disease." (PMID 36986610, 2023). "The most promising enzymes, whose inhibition is considered helpful in the pathology of Alzheimer’s Disease (AD), may be acetylcholinesterase (AChE) and butyrylcholinesterase (BChE)." (PMID 37242476, 2023). "Therefore, inhibition of AChE is the most effective therapeutic approach to restore ACh concentrations in the brain and slows down Alzheimer’s disease (AD) symptoms." (PMID 37630258, 2023). "Accordingly, the clinical neuroprotective application of AChE inhibitors has been proposed for neurological disorder diseases, including Alzheimer’s disease, senile dementia, ataxia, Parkinson’s disease, and myasthenia gravis, based on its effect on the beta-amyloid metabolism." (PMID 36005587, 2022). "Therefore, both the enzymes AChE and BuChe are being abundantly explored for their activity in the management of Alzheimer’s disease." (PMID 35956919, 2022). "The only AChE inhibitor that is approved to treat all stages of Alzheimer’s disease is donepezil." (PMID 35741617, 2022). "A previous meta-analysis reported that taking one of the AchE inhibitors (donepezil hydrochloride) for 24–26 weeks reduced the Alzheimer’s Disease Assessment Scale-Cognitive Subscale (ADAS-cog) score of patients with mild-to-moderate AD by an average of 2.67 points." (PMID 35986297, 2022). "The N-butanol extract was proven to be the main active fraction, and C. teeta may be the best source of RC drugs for Alzheimer’s disease treatment, with significantly lower IC 20, IC 50 and IC 80 values for AChE inhibition." (PMID 36388527, 2022). "Matrine structure can restore Th17/Treg cytokine balance and alleviate cognitive impairment in Alzheimer’s disease rats in a dose-dependent manner; MT can improve scopolamine-induced amnesia by inhibiting acetylcholinesterase (AChE) and butyrylcholinesterase (BuChE) activities." (PMID 36110092, 2022). "In further addition, ellagic acid inhibited AChE in an animal model of Alzheimer’s disease." (PMID 36678510, 2022). "vulgare and syringic acids, which have anti-AChE activity and beneficial antioxidant capacity, can be highlighted as potential candidates for the development of drugs for the treatment of Alzheimer’s disease and other diseases characterized by a cholinergic deficit." (PMID 36296692, 2022). "Conclusively, this study represents the first for the anti-cholinesterase activities and chemical profiling of A. lucidior and A. procera leaves, alongside the potential of normethyl budmunchiamine K as a lead drug for designing new AChE inhibitors for Alzheimer’s disease treatment." (PMID 36501324, 2022). "Additionally, a fascinating molecular modeling investigation showed that our nucleoside demonstrated good binding inhibition of AChE enzyme towards advancing an efficient medication against Alzheimer’s disease." (PMID 37621349, 2022). "Recently, it has been reported that antioxidants inhibit enzymes such as butyrylcholinesterase (BChE), acetylcholinesterase (AChE), α-amylase, carbonic anhydrase, and α-glycosidase, which are associated with diseases such as type 2-DM (T2DM), Alzheimer’s disease (AD), and glaucoma." (PMID 36144638, 2022). "The main function of AChE is the rapid hydrolysis of the neurotransmitter acetylcholine (ACh) on the cholinergic synapses associated with Alzheimer’s disease (AD), whereas butyrylcholinesterase (BChE) is not correlated with any physiological abnormalities." (PMID 35630752, 2022). "Alternation of the AChE activity could restore the cholinergic balance by inhibiting Ach hydrolysis, which might minimize the progress of Alzheimer’s disease and enhance cognitive function." (PMID 36005587, 2022).
Alzheimer disease (continued). "They found that sarsasapogenin inhibited key enzymes involved in Alzheimer’s disease pathogenesis, including acetylcholinesterase (AChE), butyrylcholinesterase (BuChE), beta-secretase 1 precursor (BACE1), and monoaminoxidase-B (MAO-B) in a concentration-dependent way." (PMID 35335393, 2022). "One of the causes of Alzheimer’s disease is a lack of acetylcholine in the brain, so aminophosphonates as acetylcholine esterase (AChE) inhibitors can be used to prevent and treat Alzheimer’s." (PMID 35721002, 2022). "AChE inhibition results in accumulation of acetylcholine leading to increased stimulation of muscarinic and nicotinic receptors which provides symptomatic relief to memory deficit in Alzheimer’s disease (AD)." (PMID 35576219, 2022). "The ability of some compounds present in P. barbatus extracts to inhibit the AchE enzyme combined with high antioxidant activity suggests that they may be a potential natural drug in the treatment of Alzheimer’s disease." (PMID 36558119, 2022). "For example, acetylcholinesterase (ACHE), which is commonly associated with β-amyloid plaques and neurofibrillary tangles in the brains of patients with Alzheimer's Disease (AD; Talesa, 2001), is not among the annotated genes for AD in the KEGG database." (PMID 36407327, 2022). "Similarly, AChE and BuChE are important enzymes in the controlling of neurodegenerative diseases, such as Alzheimer’s disease, a new additional secondary complication of diabetes mellitus." (PMID 36297317, 2022). "Therefore, restoring acetylcholine by inhibiting AChE and BChE with phytoconstituents from plants is the modern method for treating Alzheimer's disease and neurodegenerative illnesses." (PMID 36573158, 2022). "Moreover, 1 and 2 showed potential AChE inhibitory activity, indicating its potential use in the treatment of Alzheimer’s disease." (PMID 36014315, 2022). "Therefore, inhibitors that bind to PAS would prevent the formation of the AChE-Aβ complex, constituting a new alternative in the treatment of Alzheimer’s disease (AD)." (PMID 35888792, 2022). "While the physiological role of AChE in the neuronal transmission is well known, it remains the focus of pharmaceutical research, directed at treatments for Myasthenia Gravis, Glaucoma, and Alzheimer’s disease (AD)." (PMID 35888792, 2022). "In addition, C. monogyna owns a high antioxidant action with inhibitory effects on Acetylcholinesterase (AchE), a property typical of medicines used to manage Alzheimer’s disease." (PMID 34885847, 2021). "As an inhibitor of cholinesterase and (AChE) and butyrylcholinesterase (BuChE) it can be applied to manage the Alzheimer’s disease, helps to maintain the balance of neurotransmitters in case of autism spectrum disorder (ASD) and attention deficit hyperactive syndrome (ADHD)." (PMID 35052591, 2021). "Finally, the development of new acetylcholinesterase (AChE) and butyrylcholinesterase (BuChE) inhibitors represents a viable approach to alleviate Alzheimer’s disease." (PMID 34071744, 2021). "Acetylcholinesterase (AchE) inhibitors have been widely recognized as an effective treatment for Alzheimer’s disease (AD) and AChE inhibitory activity of compounds from V. officinalis (sesquiterpenes and a monoterpenoid) have been also validated in mice both in vitro and in vivo." (PMID 33922184, 2021). "Hence, AChE inhibitors are considered to be one of the most efficient approaches for the treatment of Alzheimer’s disease (AD) by enhancing cholinergic objectives in AD patients." (PMID 34361659, 2021). "However, controlled treatment with AChE inhibitors can provide some therapeutic relief to Alzheimer’s disease patients by creating a localized overexpression of AChE." (PMID 34066904, 2021).
Alzheimer disease (continued). "For a long time, the great potential of coumarin-triazole hybrids in anti-Alzheimer’s disease drug discovery has been well demonstrated by the target-based screening of acetylcholinesterase (AChE), butyrylcholinesterase (BuChE), and β-secretase (BACE1) inhibitors." (PMID 34869223, 2021). "The acetylcholinesterase enzyme (AChE) is the key enzyme in the hydrolysis of the neurotransmitter acetylcholine and is the target of most of the clinically used drugs for the treatment of Alzheimer’s disease." (PMID 33557071, 2021). "Moreover, another in silico study showed that all tested cannabinoids possessed the ability to inhibit both AChE and butyrylcholinesterase, which is a second enzyme involved in the pathogenesis of Alzheimer’s disease." (PMID 33919010, 2021). "In addition, we investigated the EEBC on neuroprotection, antioxidation, and Alzheimer’s disease (AD) marker molecules, acetylcholinesterase (AChE), and amyloid-β (Aβ)." (PMID 33917273, 2021). "Furthermore, NTCT inhibited acetylcholinesterase (ACHE), a well-known enzyme that plays an important role in Alzheimers disease." (PMID 34944409, 2021). "Current studies show that an AChE inhibitor based on the “cholinergic hypothesis” is the main drug in the treatment of Alzheimer’s disease." (PMID 34361800, 2021). "These compounds exhibited potential abilities in inhibiting BACE1 and acetylcholinesterase (AchE) that might provide a new template for the development of new anti-Alzheimer ́s disease drugs." (PMID 34356949, 2021). "This increases AChE activity in the cortex and levels of oxidative stress and proinflammatory cytokines in the hippocampus, as well as increased levels of APP and Tau by producing amyloid beta to induce neurodegeneration that can cause Alzheimer's disease." (PMID 33987539, 2021). "Alzheimer’s disease (AD) is an important illness; a current drug-discovery strategy wants to develop agents with multiple potencies, including inhibition of acetylcholinesterase (AChE)." (PMID 35194457, 2021). "A novel series of coumarin derivatives linked to the N-benzyl triazole group were synthesized and evaluated against 15-lipoxygenase (15-LOX), and acetyl- and butyrylcholinesterase (AChE and BuChE) to find the most potent derivative against Alzheimer’s disease (AD)." (PMID 35127652, 2021). "However, the recent study has reported that saliva AChE can be used as potential biomarkers to indicate the significant impairment of the cholinergic system and memory impairment in patients with Alzheimer's disease." (PMID 32685097, 2020). "The enzyme AChE is located in the synaptic gaps and neuromuscular junctions and its reversible inhibition is used as an approach to treat gastrointestinal disorders and Alzheimer’s disease." (PMID 32708417, 2020). "It has previously been reported that the flavonol quercetin and some polyphenol-rich extracts are able to inhibit the enzymes anticholinesterase (AChE) and butyrylcholinesterase (BChE), demonstrating thereby neuroprotective effect against pathologies such as Alzheimer’s disease." (PMID 32580356, 2020). "One example in the neurological context is the “sponging” activities of U1 ncRNA, which carries a complementary sequence to hsa-miR-125b-5p that has recently been shown to target AChE mRNA, and the levels of which are altered in brain cells from Alzheimer’s Disease patients." (PMID 33163005, 2020). "The cholinergic deficit in Alzheimer’s disease is a well-known phenomenon, and the restoration of cholinergic function by inhibiting the (acetylcholinesterase) AChE and butyrylcholinesterase (BChE) activity is an effective treatment strategy for Alzheimer’s disease." (PMID 33374338, 2020). "Herein, our findings strongly suggest that RECA may offer therapeutic potential for the treatment of Alzheimer’s disease through inhibiting the AChE, inflammation, and oxidative stress activities." (PMID 32079355, 2020). "Levels of AChE and BChE in the brain are increased in Alzheimer’s disease." (PMID 31752064, 2020).
Alzheimer disease (continued). "As a result, since AChE inhibition is an important task in the treatment of Alzheimer’s disease, these compounds may have an interesting future for the development of new drugs to neurodegenerative disorders." (PMID 32249705, 2020). "Both AChE and BChE enzymes are responsible for lowering the level of acetylcholine in the synaptic cleft of the brain leading to neurodegenerative disorders—namely, Alzheimer’s disease, Parkinson disease, and cognitive problems." (PMID 32392806, 2020). "AChE is an attractive target and considered a therapeutically relevant strategy for drug design and discovery for the treatment of peripheral diseases, such as Alzheimer’s disease." (PMID 32560471, 2020). "Physostigmine, the first AChE inhibitor known to man, is a carbamate readily passing the blood–brain barrier that has been used in the therapy of atropine poisoning, myasthenia gravis, Alzheimer’s disease, and glaucoma." (PMID 31191210, 2019). "Heart rate dysregulation manifesting as bradycardia has been noted in several trials of acetylcholinesterase (AchE) inhibitors for Alzheimer’s disease, and this observation has been discussed in pharmacovigilance reports; the gene encoding AchE, ACHE, has been linked to tachycardia by GWAS49,50." (PMID 30952858, 2019). "AChE has also been shown to influence gastrointestinal and colon motility and its reversible inhibition can help treat gastrointestinal (GI) disorders and Alzheimer’s disease." (PMID 31652501, 2019). "Moreover, LPE also shows a neuroprotective effect for its ability to inhibit AChE activity, an enzyme involved in Alzheimer’s disease." (PMID 31817563, 2019). "It is reported that quercetin as well as some polyphenolic-rich extracts inhibit the enzymes anticholinesterase (AChE) and butyrylcholinesterase (BChE), thus improving cognitive abilities in Alzheimer’s disease, supporting a neuroprotective role of polyphenols." (PMID 31861633, 2019). "In addition to galantamine, the anti-inflammatory effects of other AChE inhibitors and cholinergic drugs clinically approved for the treatment of Alzheimer’s disease, such as donepezil and rivastigmine, have also been demonstrated." (PMID 31024226, 2019). "Moreover, fucosterol exhibits inhibitory activity against acetyl- and butyryl-cholinesterase (AChE and BChE) and β-secretase (an enzyme responsible for Aβ production, which is related to Alzheimer’s disease)." (PMID 31766220, 2019). "Acetylcholinesterase (AChE) is an enzyme that hydrolyzes acetylcholine in the nervous system, and it is a target enzyme for drug development in neurodegenerative disease, including Alzheimer’s disease (AD)." (PMID 31847089, 2019). "In our previous work concerning natural anti-Alzheimer’s disease (anti-AD) drugs from marine sources, eckol from Ecklonia stolonifera showed selective inhibition of acetylcholinesterase (AChE) and β-site amyloid precursor protein-cleaving enzyme 1 (BACE1), but not butyrylcholinesterase (BChE)." (PMID 30744179, 2019). "In summary, further clinical trials and structural modifications may lead to the discovery of promising inhibitors of AChE, and could contribute to the treatment of Alzheimer’s disease (AD)." (PMID 30823444, 2019). "The significant AChE inhibitory activity suggests that the extract may be beneficial in the treatment of Alzheimer’s disease." (PMID 29881425, 2018). "The infusion and its active components could emerge as natural antioxidants, or serve as raw materials for the isolation of effective AChE inhibitors, thus being a promising potential complementary source against Alzheimer's disease and related diseases." (PMID 29734888, 2018). "Furthermore, in the late stage of Alzheimer’s disease, the level of AChE was found to drop to 55–67% of normal value, while BChE activity increases up to 120%." (PMID 29463056, 2018). "Thus these molecules can be very novel potentialinhibitors against AChE involved in Alzheimer's disease." (PMID 30310249, 2018).